PLK1 (polo like kinase 1)
Diseases named in the same sentence as PLK1 in open-access papers (continued):
Sharing a sentence is not in itself a finding about the gene and the disease.
cancer (continued). "Additional studies aimed at disclosing all of the molecular mechanisms of PLK1 signaling in cancers are needed to achieve the full therapeutic potential of an anti-PLK1 drug." (PMID 28953239, 2017). "An RNAi screen for factors whose depletion inhibits the growth of mutant KRAS G12D-expressing cancer cell lines identified PLK1 and components of the APC/C ubiquitin-conjugating holoenzyme." (PMID 28807782, 2017). "BI 2536 specifically inhibits Plk1 functions in mitosis, which suppresses cell division and increases apoptosis in HeLa cancer cells." (PMID 28430578, 2017). "Polo-like kinase-1 (PLK1) plays a major role in driving mitotic events, including centrosome disjunction and separation, and is frequently over-expressed in human cancers." (PMID 29170437, 2017). "The identification of the diverse roles of PLK1 throughout the course of tumor development highlights PLK1 as one of the most appealing anti-cancer drug targets." (PMID 28953239, 2017). "Here we identify that Polo-like kinase 1 (Plk1), a key regulator for cell mitosis, plays a critical role for biosynthesis in cancer cells through activating pentose phosphate pathway (PPP)." (PMID 29138396, 2017). "From these evidences it appears that PLK-1 plays a major role in inducing drug resistant in different type of cancers." (PMID 28415805, 2017). "And, miRNA-100 can also exert as a tumor suppressor in many cancers by targeting polo-like kinase 1 (PLK1)." (PMID 28977982, 2017). "Genetic modulation of the pathway linking PLK1 to APC/C activation curtailed the proliferation of mutant KRAS G12D-expressing cancer cells, while ATP-competitive PLK1 inhibitors suppressed their growth as xenografts." (PMID 28807782, 2017). "In this short review, we will summarize recent advances and future directions toward developing therapeutics against one of the most appealing anti-cancer drug targets, Plk1." (PMID 28721210, 2017). "Further understanding of the role of Plk1 in the SAC is required to evaluate the efficacy of cancer therapy targeting this kinase." (PMID 28821799, 2017). "Many cell regulators and DNA damage response players, such as cyclinD1 29, 30, PLK1 31, 32 and BRCA1 20, 33, are mutated or dysregulated in cancers." (PMID 28058814, 2017). "Because overexpression of Plk1 has been reported in many human cancers, it is regarded as a potential prognostic marker for cancer patients." (PMID 27902479, 2017). "Nowadays, PLK1 inhibitors are being used in several types of cancer patients to monitor their efficacy and safety in clinical trials." (PMID 28724602, 2017). "It has been suggested that PLK1 controls cancer development through multiple mechanisms that include the canonical regulation of mitosis and cytokinesis, as well as modulation of DNA replication and cell survival." (PMID 28953239, 2017). "Cancer cells display characteristics of sustaining proliferative signaling, evading growth suppressors, and resisting cell death, and Plk1 is involved in all these processes." (PMID 27902479, 2017). "Various studies have demonstrated that antisense oligonucleotides, small interfering (si)RNA, phosphopeptides and small molecules-based inhibition of PLK-1 is a promising approach for combating deadly cancer." (PMID 28415805, 2017). "It has been suggested that PLK1 controls cancer development through multiple mechanisms that include canonical regulation of mitosis and cytokinesis, modulation of DNA replication, and cell survival." (PMID 28953239, 2017). "Long-term PLK1 inhibition arrests cells in prometaphase, and thus PLK1 inhibitors are investigated as antimitotic agents for cancer treatment." (PMID 28102733, 2017).
cancer (continued). "Collectively, these findings establish a critical role for Plk1 in regulating biosynthesis in cancer cells, exemplifying how cell cycle progression and metabolic reprogramming are coordinated for cancer progression." (PMID 29138396, 2017). "It has been shown that PLK-1 is one of the major players in mitosis during cell cycle progression, and its’ inhibition is a promising approach for combating deadly cancers." (PMID 28415805, 2017). "Recently we and others have demonstrated that targeting PLK1 with the small molecule inhibitors BI 2536 and BI 6727 reduced cancer cell proliferation." (PMID 29228610, 2017). "Since reversing addicted protein functions has proven to be an attractive strategy to selectively kill cancer cells, addiction to overexpressed Plk1 exacerbates the vulnerability of cancer cells to Plk1 interrogation." (PMID 28721210, 2017). "Consistently, PLK1 inhibition mitigates autophagy in cancer cells both under nutrient starvation and sufficiency, and a role of PLK1 in autophagy is also observed in the invertebrate model organism Caenorhabditis elegans." (PMID 28102733, 2017). "Aberrant activation of either Aurora A or Plk1 can promote the development of cancer and they represent promising targets for anticancer therapeutics." (PMID 28402276, 2017). "Volasertib (BI 6727) is a PLK1 inhibitor and has been reported as a potential therapeutic agent in multiple cancer types." (PMID 29186071, 2017). "Mechanistic target of rapamycin complex 1 (MTORC1) and polo like kinase 1 (PLK1) are major drivers of cancer cell growth and proliferation, and inhibitors of both protein kinases are currently being investigated in clinical studies." (PMID 28102733, 2017). "Many pathways related to cancer have been identified by the pathway analysis, among which “cell cycle” and “PLK1 signaling events” are two of the most enriched pathways." (PMID 29383106, 2017). "The current rationale behind targeting PLK1 for anti-cancer therapy lies in its multifaceted functions throughout the cell cycle that target cancer’s sustaining proliferative signaling." (PMID 28953239, 2017). "PLK1 is commonly overexpressed or over-activated in cancer, and is the target of several promising drugs in late stage clinical trials." (PMID 28178660, 2017). "PLK1 is considered to be a highly promising cancer therapeutic target and several PLK1 inhibitors have shown promising results in clinical trials to date." (PMID 29170437, 2017). "We have identified a number of protein kinase genes which are upregulated commonly in cancers and are involved in the cell cycle regulation such as PLK1, TTK, BUB1, BUB1B, and PKMYT1." (PMID 28427185, 2017). "Most of these kinase genes have been shown to be overexpressed in various cancers such as PLK1, TTK, and AURKA/B." (PMID 28427185, 2017). "As PLK1 is overexpressed in several cancer cells, it has been recognized as an attractive target for cancer therapy and many PLK inhibitors are under investigation." (PMID 29108241, 2017). "Mutant KRAS expression is proposed to trigger abnormalities in progression through mitosis (“mitotic stress”) that render cancer cells sensitive to PLK1 inhibition." (PMID 28807782, 2017). "PLK1 is overexpressed in a variety of human tumors, and its expression level often correlates with increased cellular proliferation and poor prognosis in cancer patients." (PMID 28953239, 2017). "With its established key role in facilitating cell cycle progression, Plk1 has been proposed as a target for cancer therapy." (PMID 29138396, 2017). "Through the bioinformatics analysis, we firmly verified that PLK1 played a vital part in the regulation of the cell cycle and contributed to cancer-related signaling pathways, thus contributing to the stepwise tumorigenesis and progression in GC." (PMID 29190933, 2017).
cancer (continued). "Here, the authors show that Plk1 activates the pentose phosphate pathway in cancer cells by directly phosphorylating glucose-6-phosphate dehydrogenase (G6PD) and that such activation is critical for cell cycle progression and cancer cell growth." (PMID 29138396, 2017). "In recent decades, PLK1 overexpression has been suggested to serve as a prognostic factor in most types of human cancers." (PMID 28724602, 2017). "Thymoquinone and its synthetic derivative poloxin was found to inhibit the serine/threonine kinase Polo-like kinase 1 (Plk1) (usually over-expressed in many types of cancers) by interfering with its intracellular localization." (PMID 28881699, 2017). "Long-term PLK1 inhibition by its inhibitors, such as BI2536, arrests cells in prometaphase and thus PLK1 inhibitors are investigated as antimitotic agents for cancer treatment considering its high expression in tumors." (PMID 28858266, 2017). "The significance of PLK1 (polo-like kinase 1) has become increasingly essential as both a biomarker and a target for cancer treatment." (PMID 29246203, 2017). "Our data, together with previous studies, demonstrate that PLK1 is a compelling potential target in many cancers, including ATRT." (PMID 29228610, 2017). "Overexpression of PLK1 has been reported in various types of cancers and thus it has been proposed as the potential target for cancer therapy." (PMID 28239299, 2017). "PLK1's essential role in mitosis, and its dysregulation in several different forms of human cancer, has prompted efforts to create small-molecule inhibitors." (PMID 28807782, 2017). "The differential requirement of PLK1 levels in cancer versus normal cells for survival makes PLK1 a particularly attractive target for anti-cancer drug discovery." (PMID 28953239, 2017). "Polo‐like kinase 1 is a validated target for cancer, and several PLK1 inhibitors have shown promising results in phase I or II clinical trials." (PMID 27878946, 2017). "In this regard, it is significant for us to demonstrate that Plk1, a key regulator that is essential for mitosis, facilitates biosynthesis in cancer cells through activating PPP." (PMID 29138396, 2017). "Consistent with our previous study in HeLa cells, phosphorylation of RSK1 and its upstream kinase MEK/ERK was significantly increased after Plk1 inhibition in cancer cells." (PMID 28430578, 2017). "Based on these results, MKN45 and MKN74 CSC-like cells exhibited different regulation of RSK1 by Plk1 compared with the cancer cells." (PMID 28430578, 2017). "PLK1 was a valid target in tumors since its inhibition induced apoptosis in proliferating cancer cells." (PMID 28030843, 2017). "Elevated PLK1 levels have been found in many cancers compared with their normal counterpart tissues." (PMID 27878946, 2017). "BI2536 (PLK-1 inhibitor)-treatment can inhibit the metformin-induced glycolysis and glutamine anaplerosis (glutamine-dependent cancer cell survival)." (PMID 28415805, 2017). "Polo-like kinase 1 (Plk1) is a promising target for cancer therapy due to its essential role in cell division." (PMID 27902479, 2017). "The combination with more cancer-specific, molecular targeting agents is suitable for the clinical development of PLK1 inhibitors." (PMID 29108241, 2017). "As one of the highly attractive mitotic targets, polo-like kinase 1 (Plk1) has been the subject of an extensive effort for anti-cancer drug discovery." (PMID 28721210, 2017). "PLK1 plays an important role in progression of the cell cycle and is known to be overexpressed in many different cancer types, which makes this gene an interesting therapeutic target." (PMID 28556483, 2017). "Some of these same mitotic genes are being investigated as emerging cancer therapy targets including ones (i.e., AURKA and PLK1) that are implicated in cancers with “poorer prognosis”." (PMID 28817068, 2017).
cancer (continued). "Many Plk1 inhibitors targeting the kinase domain have been identified and some are currently tested in clinical trials for cancer treatment, such as BI6727 (volasertib), ON01910 (rigosertib), BI2536, GSK461364, and HMN-214." (PMID 27902479, 2017). "Over the years, PLK1 has been the subject of an extensive effort in developing anti-mitotic agents that primarily target fast-growing mitotic cancer cells while leaving normal cells unscathed." (PMID 28953239, 2017). "Bora, a critical player of the Aurora A-Bora-Plk1 axis in controlling cell cycle progression, is a candidate prognostic biomarker and potential therapeutic targets in cancer." (PMID 28402276, 2017). "The apparent correlation between the present anti-parasite data and those noted previously for inhibition of PLK1 in human cancer cells suggests that SAR studies with the respective human and schistosome PLK orthologs should be considered." (PMID 26751972, 2016). "Inhibition of PLK1 by siRNA in cancer cells in vitro has been shown to result in mitotic arrest and subsequent apoptosis demonstrating killing of cancer cells." (PMID 26934445, 2016). "The current dogma in the field implies that PLK1 controls cancer development through multiple mechanisms, including canonical regulation of mitosis and cytokinesis as well as modulation of DNA replication and cell survival." (PMID 27003818, 2016). "PLK1 is involved in checkpoint recovery and resuming cell cycle progression after DNA damage-induced cell cycle arrest; it is overexpressed in human cancers." (PMID 26934445, 2016). "The expression and activity of PLK 1 is elevated in tissues and cells with high mitotic index, such as cancer cells." (PMID 26820885, 2016). "PLK1 is overexpressed during cancer development and plays a critical role in cell division as a major cell cycle regulator controlling entry into mitosis and regulating the spindle checkpoint." (PMID 26934445, 2016). "Plk1 levels are elevated in cancer and several types of cancer cells are hypersensitive to Plk1 inhibition." (PMID 27874094, 2016). "Many cancer cell types are more sensitive than healthy cells to a reduction in Plk1 function, and this difference defines a theoretically exploitable therapeutic window." (PMID 27874094, 2016). "Polo-like kinase 1 (Plk1) plays several roles in cell division and it is a recognized cancer drug target." (PMID 27874094, 2016). "Polo-like kinase 1 (Plk1) is an essential cell cycle regulator and a target for cancer drug development." (PMID 27874094, 2016). "We found several mitotic regulators, including PLK1, exhibited significant higher mRNA expression, compared to normal tissue, across 24 different types of cancers." (PMID 27557495, 2016). "Cancers including breast, ovarian, endometrial, prostate, and colorectal are found to have such elevated expression and activity of PLK1." (PMID 26820885, 2016). "Given its well-established functions in regulating cell cycle and promoting proliferation in human cancers, we singled out PLK1 for further study in hyperplastic VSMC." (PMID 26820885, 2016). "The “Hallmark apoptosis”, a common feature of cancers, was enriched with APC/C-mediated degradation of cell cycle protein, Cyclin B2 mediated events and PLK1 signaling events, highlighting their roles in the development of cancers." (PMID 27991568, 2016). "Identification of the CRAF-MEK1/2-ERK1/2 signaling cascade as an essential downstream effector of PLK1 in prostate epithelial cells corresponds with the known roles of this cascade in the pathogenesis of various types of cancer, including PCa." (PMID 27003818, 2016). "On the other hand, MPLKIP is expressed in fetal skin and fibroblasts, while PLK1 expression is highest in tissues with actively proliferating cells (e.g. gonads, cancers)." (PMID 26880286, 2016). "Several small-molecule PLK1 inhibitors have been developed as cancer therapeutics in recent years and are under investigation in clinical trials." (PMID 26046302, 2016).
cancer (continued). "In line with this evidence, not only the depletion of MPS1 but also that of PLK1 had a preferential cytotoxic effect on tetraploid as compared to diploid cancer cells." (PMID 26637805, 2016). "It has been suggested that PLK1 controls cancer development through multiple mechanisms that include canonical regulation of mitosis and cytokinesis, as well as modulation of DNA replication and cell survival." (PMID 27003818, 2016). "Inhibition of PLK-1 in vitro leads to cell cycle arrest at G2/M and apoptosis in human cancer cell lines." (PMID 26754547, 2016). "PLK-1 mRNA is over-expressed in most human cancers including those of the breast, lung, stomach, colon and rectum, ovary, pancreas and prostate." (PMID 26754547, 2016). "PLK1 overexpression has been documented in various cancers and has been implied in their malignant phenotype." (PMID 26046302, 2016). "Due to PLK1 altered expression in a wide range of cancers and to its roles in cancer progression, it was the chosen target to siRNA therapy." (PMID 26085038, 2015). "SBE13, a selective type II Plk1 inhibitor, is able to induce a delay in cell cycle progression, to reduce cell proliferation and to induce apoptosis in a broad range of human cancer cell lines." (PMID 26317649, 2015). "Phase I and II clinical therapeutic trials have been evaluated using siRNAs to inhibit critical cancer-associated genes, including siRNA-EphA2-DOPC (targeting EphA2), TKM-080301 (targeting PLK1), and CALAA-01 (targeting RRM2)." (PMID 26448935, 2015). "Plk1 is an essential kinase for mitotic progression that is overexpressed in many cancers, including NSCLC." (PMID 25714019, 2015). "In cancer cells, PLK1 depletion has been shown to inhibit cell proliferation, perturb spindle assembly, prolong mitotic arrest, and induce apoptosis." (PMID 26008977, 2015). "Given that targeting PLK1 and Aurora kinases resulted in cytotoxicity in cancer cells (HeLa), we next evaluated the cytotoxicity on a cancer versus normal cells model." (PMID 25871386, 2015). "Apart from the cell cycle, the cluster corresponding to PLK1 signalling (H047; n = 30, p = 3.4E-004) (an important signalling pathway mediated by “polo like kinase” in a wide range of cancers) displays exceptionally high networked properties unique to CM." (PMID 26558755, 2015). "A number of cellular proteins, including Aurora kinase A, Plk1, Chk1, Chk2, Cyclin B1, and Cdk1, regulate centrosome duplication and the abnormal upstream regulation of these proteins is found in various cancers." (PMID 25999914, 2015). "Depletion or inhibition of kinase activity of PLK1 is sufficient to induce cell-cycle arrest and apoptosis in cancer cell lines and in xenograft tumor models." (PMID 25574601, 2015). "In conclusion, cancer cells appear to be more sensitive to pharmacological inhibition of PLK1 than normal cells." (PMID 25871386, 2015). "PLK1 was previously shown to be overexpressed in various types of cancers and is known to be responsible for the aberrant proliferation of cancer cells." (PMID 26503893, 2015). "Irrespective of the mechanism, the higher sensitivity of NPC cells to PLK1i offers a rationale for targeting PLK1 in the management of this cancer." (PMID 25871386, 2015). "Plk1 is one of the most promising targets for molecular cancer treatment and its inhibitors block efficiently proliferation of various cancer cells including MDA-MB-231 and MCF-7 cells." (PMID 26439686, 2015). "The functional relevance of Plk1 has been demonstrated in vitro by ‘knock-down’ experiments in cancer cell lines." (PMID 25794535, 2015). "Inhibition of PLK1 has been reported to induce apoptosis in a number of different types of cancer cells via a G2/M cell cycle arrest." (PMID 25557168, 2015). "PLK1 is recognized as a drug target for cancer therapeutics, and intense research has been devoted to the development of chemical molecules which inhibit the function of PLK1." (PMID 25557168, 2015).